MMP9 (matrix metallopeptidase 9)
Diseases named in the same sentence as MMP9 in open-access papers (continued):
Sharing a sentence is not in itself a finding about the gene and the disease.
cancer (continued). "Silencing of TM4SF1 also increases the expression of TIMP (an inhibitor of MMP), inhibits the expression of pro-angiogenic genes (uPA, MMP-2, MMP-9, and VEGF) and suppresses the proliferation, invasion and metastasis of cancer cells." (PMID 27153056, 2016). "In tissue culture and in the liver colonies derived from cancer cells with knockdown of S100A8 and S100A9, MMP2 and MMP9 expression was decreased, consistent with the reduction in migration and invasion." (PMID 27086923, 2016). "Growth of both cancer cell lines expressing MMP-2 and MMP-9 was stopped, and the cell number was reduced at 24 h and remained low during an observation period of 96 h." (PMID 27295081, 2016). "One of the limitations is - such type of ionizing radiation can enhance the metastatic nature in various kinds of cancer cells by increasing the expression as well as activities of MMP-2 and MMP-9 leading to great difficulties in radiotherapy." (PMID 27659937, 2016). "Our data also showed that accompanied with the increasing of VE- cadherin, CD133+ cancer stem-like cells had the higher level of MMP-2 and MMP-9." (PMID 27074560, 2016). "It has been documented that NF-κB is critically important for MMP-9 to mediate cancer cell invasion, and the binding of CREB to promoter is centrally involved in MMP-2 gene expression and related to the malignancy of cancer cells." (PMID 27144433, 2016). "ERK-induced MMP-2 and MMP-9 have been reported to degrade extracellular matrix, provoking cancer cell invasion into stroma; therefore, we used gelatin zymography to evaluate MMP-2 and MMP-9 activities at different miR-550a-5p concentrations." (PMID 27462780, 2016). "Previous studies showed that FOXM1 promotes cancer cell migration and invasion by increasing the activities of MMP2 and MMP9." (PMID 27034162, 2016). "Overexpression of MMP1, MMP2, MMP3, MMP7, MMP9, and MMP13 correlates with worse outcomes in cancer patients." (PMID 27908290, 2016). "A comparatively higher level of MMP9 protein is however noted in RWPE-1 (normal-derived) and PC3 (cancer-derived) cells than in the rest of the cell lines." (PMID 27331624, 2016). "Taken together, our data indicate thatquercetin is an effective anti-cancer agent against MMP-2- and MMP-9-mediatedmetastasis in EGFR-overexpressing HNSCC." (PMID 27510965, 2016). "We observed in this study that both MMP-2 and MMP-9 protein levels and activity are downregulated in the presence of WJ-MSCs and fd-ECM, clearly showing that both MSCs and fd-ECM have an effect on “cancer survival” genes." (PMID 26880967, 2016). "MMPs help cancer cells spread by breaking down the extracellular matrix (ECM) and other barriers MMP-2 and MMP-9 were previously reported to be involved in human tumorigenesis and cancer metastasis." (PMID 27042161, 2016). "Matrix metalloproteinases are important contributors to the invasive and metastatic properties of cancer cells, their expression (especially MMP-2 and MMP-9) being elevated in a range of carcinomas." (PMID 28933410, 2016). "Expression of miR-204 was significantly down-regulated in cancer and OSMF tissues, while expression of its three target genes (MMP9, PLAUR and SERPINE1) showed significant up-regulation in cancer only." (PMID 27597234, 2016). "For resveratrol, studies have demonstrated its anti-metastatic effect against several types of cancers by downregulation of MMP expression and its enzymatic activities, mainly MMP-2 and MMP-9." (PMID 27834913, 2016). "MMP-9 showed its ability to fairly diagnose COPD (AUC: 0.68) and cancer (AUC: 0.67) in healthy subjects." (PMID 27811960, 2016). "POSTN also functions as a driver of EMT and induces expression of matrix metalloproteinase (MMP)-9, -10, and -13, resulting in the degradation of extracellular matrix (ECM), and promoting cancer spread and metastasis." (PMID 26556874, 2016).
cancer (continued). "MMP-9, usually up-regulated during EMT in cancer cells, is a matrixin belongs to the zinc-metalloproteinases family degrading the extracellular matrix, which is important for angiogenesis, wound healing, cell migration, and angiogenesis." (PMID 27191743, 2016). "In particular, MMP2, MMP9 and MMP14 have all been shown to promote cancer progression due to their ability to degrade basement membrane components." (PMID 27789576, 2016). "Among the matrix metalloproteinases, MMP-9, and also MMP-2, which are highly expressed in various malignant tumors, are crucial in the degradation of type IV collagen, and are considered to be associated with invasion and migration of malignant cells." (PMID 27110764, 2016). "An increase in the expression of MMP-9 was shown to correlate with clinical stage of BCC and more aggressive phenotype of this cancer." (PMID 27406386, 2016). "The synergistic combination of metformin and MEK-Is strongly inhibited the binding of NF-κB to the MMP9 and MMP2 promoters, thereby suppressing their expression and the metastatic potential of cancer cells." (PMID 26673006, 2016). "Silencing of 5-HT7 (but not of 5-HT1D) receptor abrogated 5-HT-induced MDA-MB-231 cell invasion, and this was accompanied by a decrease in the expression of matrix metalloproteinase-9 (MMP-9), a positive regulator of cancer cell invasion." (PMID 27871326, 2016). "Aberrant FOXM1 expression enhances the migration and invasion of cancer cells by upregulating the transcription levels of MMP2 and MMP9." (PMID 27034162, 2016). "It is reported that the downregulation of MMP-9 via GPR54 and ERK-MAPK signaling pathway was involved in the inhibitory effect of KiSS1 on the migration and invasion of cancer cells." (PMID 27287327, 2016). "MMP1 and MMP14 have been reported to induce cancer cell invasion, and MMP14 is further recognized in the activation of MMP2 and MMP9." (PMID 26981862, 2016). "Due to the function of MMP-9 in the course of malignancy, the suppression of MMP-9 levels is an important strategy for controlling cancer." (PMID 25875631, 2015). "Matrix metalloproteinases (MMPs) are highly involved in degradation of extracellular matrix, a key process of cancer metastasis, MMP2 and MMP9 are the principal enzyme involved and reported to be overexpressed in OSCC." (PMID 26540630, 2015). "Positive correlations (|r|>0.45) among CRP, IL-6, TNF-α, IL-1β, MMP-9, VEGF, and TF antigen were found in both groups of cancer patients, whereas the fibrinogen correlated only in DVT+ group." (PMID 26192925, 2015). "Since MMP2 and MMP9, which were suggested to play essential functions on ECM degradation and promote invasiveness of cancer cells, the expressions and activities of MMP2 and MMP9 were determined by qRT-PCR and ELISA assay." (PMID 26177288, 2015). "Next, we detected the expression levels of MMP-2 and MMP-9, which are regulated by FAK and are critical for cancer cell invasion." (PMID 25689564, 2015). "These merged DMxDE datasets suggest some known or previously reported/suspected cancer genes [PR: SPARCL1, NQO1, CST1, MELK1, DPT, FAM83A, MMP9; GB: FOXM1, TFAP2, GREM1, ITGA8, GRIA1, SLIT3] as well as many previously unreported genes/loci." (PMID 26683690, 2015). "The overexpression of PP4C promoted cancer cell growth and invasion and markedly increased the MMP-2/MMP-9 activities through a PI3K/AKT-dependent signaling pathway." (PMID 25927939, 2015). "The degradation of the extracellular matrix (ECM) and basement membrane are crucial steps in cancer invasion and metastasis and the proteolytic enzymes MMP-2 and MMP-9 are involved in this process." (PMID 26512779, 2015). "Matrix metalloproteinases (MMPs), especially MMP1 and MMP9, are critical enzymes responsible for the degradation of the basement membrane (BM) and extracellular matrix (ECM), thereby contributing to cancer invasion and metastasis." (PMID 26337460, 2015).
cancer (continued). "It has been shown in breast, prostate and other cancers that soy isoflavones can inhibit cell detachment, invasion and the expression of proteases such as MMP-2 and MMP-9." (PMID 25655427, 2015). "MMP-2 and MMP-9 are two key regulators of extracellular matrix (ECM) remodeling and play a crucial role in angiogenesis, migration of cancer cells and metastasis." (PMID 25619880, 2015). "The correlation between the expressions of MMP9 and HPSE in cancer progression; has been observed previously in different types of cancer." (PMID 26084486, 2015). "Hydration of the extracellular matrix is crucially important for cancer cell invasion and metastasis, a process that tumor cells promote through the secretion of proteins such as matrix metalloproteinase-2 (MMP-2) and MMP-9." (PMID 25402510, 2015). "We have found an increasing release of inflammatory cytokines, MMP-9 and VEGF in monocytes from two groups of cancer patients with the highest release levels in the group with DVT." (PMID 26192925, 2015). "We have shown that IWR-1 significantly reduces the MMP2 and MMP9 activities in the cancer cells, even in the presence of TNF-α-induced cancer cell stimulation." (PMID 26450645, 2015). "It was previously reported that cancer cells recruit BMDCs through secretion of soluble factors, including SDF-1, VEGF, MMP-9, placental growth factor (PIGF), IL-1 beta, and granulocyte macrophage colony stimulating factor (GM-CSF)." (PMID 26416452, 2015). "MMPs, particularly MMP-2 and MMP-9, are key enzymes known to degrade the components of surrounding ECM during cancer invasion and metastasis." (PMID 25803820, 2015). "TPA has been reported to promote cancer cell motility through regulating the expression and function of S100A14, cyclooxygenase-2 (COX-2) or matrix metalloproteinase-9 (MMP-9)." (PMID 25915860, 2015). "To further confirm that WIP1 accelerated cancer progression in vitro and in vivo, we delineated the correlation between WIP1 and MMP-9 and VEGF-C to determine how WIP1 promoted ACC-M cells migration and invasion." (PMID 25797250, 2015). "Negative immune-expression of TIMP1 is correlated with biochemical recurrence in patients with PC possibly by failing to control MMP-9, an important MMP related to cancer progression." (PMID 26742965, 2015). "The relationship between CD147 and MMP-9, MMP-2 and their relevance with patients’ prognosis and clinicopathological parameters have been studied in a variety of cancers." (PMID 26507719, 2015). "Calcium independent group VIA phospholipase A2 (iPLA2β) and Matrix Metalloproteinase-9 (MMP-9) are upregulated in many disease states; their involvement with cancer cell migration has been a recent subject for study." (PMID 26588686, 2015). "In summary, we have identified myeloid cells that express CCR1, MMP9 and MMP2 to promote cancer metastasis." (PMID 25326065, 2014). "Matrix metalloproteinase-9 (MMP-9), which degrades the extracellular matrix, is a major component in cancer cell invasion." (PMID 24885456, 2014). "MMP-2 and MMP-9 play important roles in cancer metastasis, and IL-17A can affect the expression of MMP-2 and MMP-9." (PMID 25244643, 2014). "MMP-9 and TIMP-2 can affect the progression of cancer, which is valuable for studies on oral and maxillofacial SCC genes." (PMID 24829764, 2014). "Previous research has demonstrated that up-regulation of FOXM1 increased the expression of MMP-2, MMP-9 and VEGF-A, resulting in the promotion of proliferation, migration and invasion of cancer cells." (PMID 24885308, 2014). "Namely, neutrophils found in the early phase of cancer cell dissemination expressed CCR1 exclusively and MMP9 preferentially, whereas fibrocytes accumulated in later phase expressed MMP2 exclusively." (PMID 25326065, 2014). "MMP-9 is a downstream signaling molecule of CXCR4 and is critical for the migration and invasion of cancer cells." (PMID 24765179, 2014).
cancer (continued). "Our results showed that P2Y2R activation by ATP or UTP induced MMP-9 activity, VEGF production and VE-cadherin phosphorylation, and these effects of P2Y2R suggest that it plays an important role in promoting cancer metastasis." (PMID 25156554, 2014). "Our results demonstrated that the level of HSP60 and MMP-9 were correlated with each other, indicating higher invasive and metastasizing activity in HSP60-positive cancer cells." (PMID 25207654, 2014). "Collectively, our data also demonstrate the role of WAVE3 in the modulation of the NFκB signaling and its downstream biological effects on MMP9- and invadopodia-mediated regulation of the ECM degradation that is required for cancer cell motility and invasion." (PMID 25329315, 2014). "We observed that HCS prevented the invasion of cancer cells, with inhibiting the expressions of MMP-2 and MMP-9, and reduced not only the number of metastasis nodules but the ratio of liver-body weight as well." (PMID 25496480, 2014). "We propose that CTHRC1 promotes cancer cell invasiveness through activation of ERK and subsequent induction of MMP9 expression." (PMID 24504172, 2014). "Our results demonstrated that the expression of ALDH1A1 and MMP-9 was correlated with each other, indicating higher invasive and metastasizing activity in ALDH1A1 overexpression cancer cells." (PMID 25253129, 2014). "Critical involvement of CCR1, MMP9 and MMP2 was verified experimentally using gene knockout mice lacking these proteins, which suggested possible therapeutic intervention of cancer progression by targeting these molecules." (PMID 25326065, 2014). "The biological significance of loss of WAVE3 and its effect on the NFκB signaling were investigated through the ability of cancer cells to form invadopodia and degrade the ECM, both of which require MMP9 activation driven by NFκB signaling." (PMID 25329315, 2014). "Matrix metalloproteinase-9 (MMP-9) is an important member of the matrix metalloproteinase family and is considered to be involved in the invasion and metastasis of cancer cells." (PMID 24476461, 2014). "MMP-9 and MMP-2 are important ECM-degrading enzymes that are involved in cancer invasion and metastasis." (PMID 25174454, 2014). "This high molecular weight MMP was revealed in the urine of cancer patients and the conclusion was that the role of NGAL is to protect the form of MMP9 involved in enzymatic degrading, thus supporting its activity." (PMID 24967433, 2014). "Several findings showed that curcumin suppresses the expression of a variety of NF-κB regulated gene products involved in cancer development and progression such as cyclin D1, VEGF, COX-2, c-myc, Bcl-2, ICAM-1, and MMP-9." (PMID 25295272, 2014). "IL-17A has been reported to promote the invasion of cancer cells via upregulating the expression of MMP-2 and MMP-9." (PMID 24905806, 2014). "Given the important role of NFκB signaling during cancer progression and metastasis through regulation of MMPs, our findings identify WAVE3 as a major player in the NFκB-mediated regulation of MMP9." (PMID 25329315, 2014). "Extensive research of MMP-9 and NGAL has demonstrated their involvement in fundamental biological processes including inflammation and cancer." (PMID 24713998, 2014). "Consistent with the results obtained in cancer, the upregulation of MMP-2 and MMP-9 also contributes to the migratory/invasive behavior of human mesenchymal stem cells (hMSC)." (PMID 24804928, 2014). "These anti-malignant phenotypes of L1CAM-knockdown cancer cells were accompanied by G0/G1 cell cycle arrest and suppression of matrix metalloproteinase (MMP)-2 and MMP-9 expression and nuclear factor NF-κB activation." (PMID 25294816, 2014). "The upregulated cancer inducing factors probed here include EMMPRIN, MMP-9, IL-6, and TGF-β1 and all were secreted upon stimulation with EVs used here." (PMID 23936495, 2013).
cancer (continued). "Heterogeneity of Forkhead box M1 (FOXM1), matrix metallopeptidase 9 (MMP9), and pituitary tumor-transforming 1 (PTTG1) were involved in cancer invasion and migration." (PMID 23577100, 2013). "Several previous studies have indicated that natural products inhibit cancer metastasis by inhibiting MMP-2 and MMP-9 expression." (PMID 23799155, 2013). "The results suggest that the anti-invasive action of tas1611 is partly mediated by diminishing the ability of cancer cells to degrade the components of the ECM by modulating the expression and activity of MMP-2 and MMP-9." (PMID 24137425, 2013). "The roles of MMP-2, MMP-9, ICAM-1, and VEGF in invasion, adhesion, and angiogenesis of cancer are well known and regulated by NF-κB." (PMID 23864892, 2013). "We also found that the MMP-3 and MMP-9 that regulate metastasis were down regulated in ASH-WEX and TEG-treated cancer cells; normal cells remained unaffected." (PMID 24130852, 2013). "It is a serine protease that converts plasminogen to plasmin, which directly mediates cancer cell invasion by degrading matrix proteins such as collagen IV, fibronectin, and laminin or indirectly by activating MMP-2, MMP-3, MMP-9, and uPA." (PMID 23878609, 2013). "Our results agree with previous studies showing that blocking IL-6 attenuates cancer cell invasiveness through down regulation of MMP-2 and MMP-9 expression." (PMID 23593315, 2013). "Among these enzymes, MMP-2 and MMP-9 can degrade most ECM components and are profoundly involved in the development of cancer invasion and metastasis." (PMID 24053256, 2013). "Our mRNA array data and bioinformatic analysis also showed that genistein targets MMP9 and VEGF genes that are components of the KEGG ‘Pathway in cancer’." (PMID 23936419, 2013). "Downstream from MAPK signaling, JNK activation helps regulate cancer cell invasion and expression of MMP-1, MMP-2, and MMP-9." (PMID 23878609, 2013). "Significantly increased mRNA expression of MMP-2 and MMP-9 and decreased expression of TIMP-1 and TIMP-2 was observed in the cancer-induced group." (PMID 23599733, 2013). "Other molecule promoting cancer cells migration and invasion like c-Met, MMP2, MMP9 were assessed by western blot." (PMID 24180482, 2013). "Some ganoderic acids and lucidenic acids have been reported to exert anti-invasive effect via suppression NF-κB signaling and down-regulation the expressions of MMP-9, MMP-2, uPA, and uPAR in various cancer cells." (PMID 24204647, 2013). "In human cancer cells, MMP-1, MMP-2, MMP-3, MMP-9, and MMP-13 have been found to be correlated with malignant grade and metastasis." (PMID 24047437, 2013). "The presence of different MMPs including HMWs (MMP9-dimer, MMP9-TIMP-1, ADAMTS-7) was reported in the urine of a variety of cancer patients including bladder." (PMID 23672427, 2013). "According to a large number of literature reports, the growth, invasion and metastasis of malignant tumors are closely related with VEGFR-2 and MMP-9, and the Gab1-mediated VEGFR-2 signaling pathway can promote cell growth and invasion." (PMID 24312291, 2013). "In summary, our data indicated that Tyr-342F phosphorylation of FOXP3 is involved in the inhibitory regulation of cancer malignancy by SKP2, VEGF-A, and MMP9 expression." (PMID 24155921, 2013). "HCT 116 cancer cells were exposed to STB-HO for 48 h and, VEGF and MMP-9 levels were measured by ELISA." (PMID 23883349, 2013). "Soy saponins were also found to have cancer-protecting ability by reducing the expression of mRNA and the amount of matrix metalloproteinases (MMP-2 and MMP-9) in HT-1080 cells." (PMID 24224098, 2013). "Although various MMPs contribute to cancer cell metastasis, the gelatinases MMP-2 and MMP-9 have been most intensively studied." (PMID 23799155, 2013).